GSN (gelsolin)
Diseases named in the same sentence as GSN in open-access papers (continued):
Sharing a sentence is not in itself a finding about the gene and the disease.
acute myeloid leukemia (2 papers, 2018 to 2023). Acute myeloid leukemia (AML) is a group of neoplasms arising from precursor cells committed to the myeloid cell-line differentiation. "Alterations in plasma gelsolin concentrations were also detected in the case of diseases involving changes in sphingolipid contents in blood and bone marrow plasma such as acute myeloid leukemia (AML)." (PMID 30149613, 2018).
atherosclerosis (2 papers, 2008 to 2018). A disease characterized by the build-up of fatty material and calcium deposition in the arterial wall resulting in partial or complete occlusion of the arterial lumen. "Thus, increased level of gelsolin seen in ApoE+/−-TLR2+/+ mice fed a high fat diet and injected with P. g may be linked to the increased apoptosis and atherosclerosis observed in this group." (PMID 18787704, 2008).
atrial fibrillation (2 papers, 2016 to 2022). A disorder characterized by an electrocardiographic finding of a supraventricular arrhythmia characterized by the replacement of consistent P waves by rapid oscillations or fibrillatory waves that vary in size, shape and timing and are accompanied by an irregular ventricular response. "The SNP with the greatest ASE difference in the LA of patients with and without postoperative atrial fibrillation was within the gelsolin (GSN) gene, previously associated with atrial fibrillation in mice." (PMID 27923400, 2016).
cardiomyopathy (2 papers, 2013 to 2025). A disease of the heart muscle or myocardium proper. "Gelsolin is upregulated and promotes apoptosis in cardiomyopathy." (PMID 23799049, 2013).
chronic lung disease (2 papers, 2012 to 2022). According to the definitions of the American and British Thoracic Societies, including pulmonary functional tests, X-rays, and CT scans for items such as fibrosis, bronchiectasis, bullae, emphysema, nodular or lymphomatous abnormalities. "Inhaled recombinant human plasma gelsolin may be an attractive new treatment for RV-induced exacerbations of BPD or preventive therapy for chronic lung disease of prematurity." (PMID 35173718, 2022). "Therapies acting against airway mucus in CF include dextran, nacystelyn, and gelsolin which possess mucolytic properties, but evidence that these agents cause sustained relief from airway obstruction in chronic lung disease is lacking." (PMID 22645424, 2012). "Collectively, our findings demonstrate a promising role for gelsolin, administered by inhalation into the airway to treat RV-induced exacerbations of BPD and prevent chronic lung disease." (PMID 35173718, 2022).
colon adenocarcinoma (2 papers, 2021 to 2023). "Furthermore, it was shown that GSN colocalizes with vinculin and actin, orchestrating cell migration and podosome formation in the colon adenocarcinoma cell line." (PMID 34685680, 2021).
cutaneous melanoma (2 papers, 2023 to 2025). A primary melanoma arising from atypical melanocytes in the skin. "Previously, we demonstrated that high levels of gelsolin (GSN) correlate with the advanced stages of cutaneous melanoma." (PMID 40597347, 2025). "Our other study indicated that human cutaneous melanoma cells with a GSN knockout exhibit significantly lower invasive and migratory potential compared to control cells." (PMID 40597347, 2025). "To determine if human skin melanoma cell lines express the studied isoforms of GSN, we performed the BaseScopeTM procedure to detect in situ transcripts coding for GSN-A, -B, and -C in selected human cutaneous melanoma cell lines: A375, WM1341D, Hs294T, and WM9." (PMID 40597347, 2025). "Additionally, elevated levels of GSN and RPSA were linked to the progression of skin melanoma and a poorer prognosis for patients." (PMID 40597347, 2025). "There are only a few publications regarding the role of GSN in skin melanoma." (PMID 40597347, 2025). "Therefore, now we aimed to investigate the function of individual GSN isoforms (A, B, C) in human skin melanoma cells regarding their motility and adhesion, as this aspect has not been examined previously." (PMID 40597347, 2025). "Therefore, nothing is known about the role of specific GSN isoforms in skin melanoma biology." (PMID 40597347, 2025). "Experiments conducted on cells lacking GSN expression have demonstrated that the isoforms of this protein do not perform the same functions in skin melanoma cells." (PMID 40597347, 2025).
Dementia with Lewy Bodies (2 papers, 2019 to 2020). "Moreover, gelsolin was found in LBs from PD and Dementia with Lewy Bodies (DLB) patients and was shown to have a positive effect on αSyn aggregation in the presence of high Ca2+ concentrations." (PMID 32903460, 2020). "Moreover, a study on the role of GSN in Lewy body diseases reported the presence of gelsolin together with α-synuclein in Lewy bodies of DLB and PD brains as detected by immunohistochemistry." (PMID 31527695, 2019).
Down syndrome (2 papers, 2013 to 2014). "Gelsolin levels increase in brain during development, and are higher in children with Down’s syndrome." (PMID 24007566, 2013). "Peripheral biomarkers of oxidative stress in Down syndrome include SOD, GPx, uric acid, plasma melatonin, urinary kynurenine, gelsolin, nitric oxide and neopterin." (PMID 24901945, 2014).
endometrial cancer (2 papers, 2025). Primary or metastatic malignant neoplasm involving the endometrium (mucous membrane that lines the endometrial cavity). "We have identified the expression levels of GSN, CAPG, AVIL, SVIL, and FLII as independent survival risk factors in endometrial cancer (EC) patients." (PMID 39964147, 2025). "The low expression of CAPG, AVIL, and SVIL, together with the high expression of GSN, VILL, and FLII, were found to be significantly associated with poor overall survival in endometrial cancer patients." (PMID 39964147, 2025). "The HPA database provided IHC images of endometrial cancer and normal endometrial tissues, allowing us to confirm the differential expression of CDKN2A, SELENOP, GSN, PGR, and TRPC1 at the protein level." (PMID 41244925, 2025).
epilepsy (2 papers, 2023 to 2024). A brain disorder characterized by episodes of abnormally increased neuronal discharge resulting in transient episodes of sensory or motor neurological dysfunction, or psychic dysfunction. "In our study, on the contrary, an increased expression of GSN was observed in the whole group of epilepsy in comparison with the healthy group, which may be caused by compensatory mechanisms." (PMID 39063177, 2024). "There is evidence of the potential of gelsolin as a biomarker for epilepsy, with people with epilepsy having considerably lower CSF levels of gelsolin than healthy controls." (PMID 38192726, 2023). "The findings suggested that haptoglobin, ceruloplasmin, α2-macroglobulin, complement factor H, and gelsolin play roles in canine epilepsy and Aβ levels based on proteomic profiling." (PMID 38192726, 2023). "Gelsolin protein levels were similarly reduced in the temporal lobe in patients with epilepsy." (PMID 38192726, 2023). "The plasma proteomic pattern was identified, and five major proteins potentially involved in the pathogenesis of epilepsy and control of Aβ levels, including HP, α2-macroglobulin, ceruloplasmin, CFH, and gelsolin, were identified." (PMID 38192726, 2023). "The plasma proteomic pattern was assessed, and five major proteins potentially involved in the pathogenesis of epilepsy and elevated Aβ levels were identified: haptoglobin (HP), α2-macroglobulin, ceruloplasmin, complement factor H (CFH), and gelsolin." (PMID 38192726, 2023).
esophageal cancer (2 papers, 2021 to 2023). A primary or metastatic malignant neoplasm involving the esophagus. "Another study confirmed these observations by showing that overexpression of GSN in human esophageal cancer cells resulted in a reduction in the number of filopodia." (PMID 34440617, 2021).
fibrosis (2 papers, 2025). the formation of excess fibrous connective tissue in an organ or tissue in a reparative or reactive process. "Mechanistically, GSN plays a role in cytoskeletal dynamics; its absence leads to impaired F‐actin depolymerization and subsequent overactivation of F‐actin, which in turn results in excessive activation of YAP, thereby aggravating hepatic fibrosis and inflammatory responses." (PMID 40390546, 2025).
glaucoma (2 papers, 2011 to 2019). Increased pressure in the eyeball due to obstruction of the outflow of aqueous humor. "Afamin (fold change, 3.3; p=0.0003) and gelsolin (fold change, 4.7; p=0.00005) were the 2 extracellular chaperones found to be differentially expressed in the AH of patients with glaucoma shunt device compared to normals." (PMID 21850163, 2011). "ONH‐specific gelsolin (Gene name: GSN), prostaglandin D synthase (Gene name: PTGDS), as well as calponin (Gene name: CNN3) were reported as glaucoma ONH astrocyte markers." (PMID 31470587, 2019).
Hepatic steatosis (2 papers, 2023 to 2025). Steatosis is a term used to denote lipid accumulation within hepatocytes. "Under MASH models, Gsn knockout (KO) (Gsn−/−) mice demonstrate exacerbated hepatic steatosis, inflammation, and fibrosis, underscoring GSN's protective function." (PMID 40390546, 2025). "It has been reported that gelsolin knock-out mice fed a high-fat diet exhibited increased body weight and fat mass, and then presented with hepatic steatosis." (PMID 37107219, 2023).
HIV-1 infection (2 papers, 2013 to 2023). The type species of lentivirus and the etiologic agent of acquired immunodeficiency syndrome (AIDS). "We next studied early HIV-1 infection using single-cycle viruses bearing the Luc-reporter gene in permissive lymphocytes overexpressing functional gelsolin." (PMID 23575248, 2013). "It is plausible that cofilin found difficulties to inhibit HIV-1 infection in cells presenting higher amounts of cortical F-actin, after knockdown of endogenous gelsolin." (PMID 23575248, 2013). "Perturbing these actin- and gelsolin-mediated events severely restricts pore fusion formation and early HIV-1 infection, which are therefore sensitive to the actin-severing activity of gelsolin at the plasma membrane, and hence, to gelsolin expression." (PMID 23575248, 2013). "Based on these findings, we propose that gelsolin can restrict early HIV-1 infection acting at a pre-fusion step, and altering the stability and dynamics of the cortical actin cytoskeleton in permissive lymphocytes." (PMID 23575248, 2013). "The amount of actin available and its arrangement in the cortex appears to be controlled by the activity of the gelsolin expressed by the cell, suggesting that gelsolin can restrict early HIV-1 infection." (PMID 23575248, 2013). "Finally, gelsolin must cleave AFs in short filaments to allow actin cytoskeleton reorganization during early HIV-1 infection steps." (PMID 37685911, 2023). "To further demonstrate the involvement of gelsolin in early HIV-1 infection, we studied the effects of silencing endogenous gelsolin expression in permissive lymphocytes with specific small interfering RNA (siRNA) oligonucleotides (oligos) against gelsolin (siRNA-GSN)." (PMID 23575248, 2013). "Accordingly, cell-signals that regulate gelsolin expression and/or its actin-severing activity may be crucial to combat HIV-1 infection." (PMID 23575248, 2013). "However, based on our results we propose that the actin-severing gelsolin protein is a novel limiting factor that controls early HIV-1 infection in permissive lymphocytes acting at a pre-fusion step." (PMID 23575248, 2013). "Thus, alteration of endogenous gelsolin expression or activity, and subsequent cortical actin amount restrict early HIV-1 infection at a pre-fusion step." (PMID 23575248, 2013). "The fine-tuning of gelsolin activity is necessary to ensure the virus-driven regulation of cell-surface receptors and of cortical actin dynamics, events that are crucial for efficient pore fusion formation and therefore early HIV-1 infection in T lymphocytes." (PMID 23575248, 2013). "Cofilin regulates early HIV-1 infection depolymerising cortical F-actin at a post-fusion step, a process that may be influenced by cortical F-actin levels, in cells where endogenous gelsolin was silenced." (PMID 23575248, 2013). "We assessed the effect of gelsolin activity on the gp120/gp41 fusion capacity in permissive HeLa P5 cells, in order to ascertain whether actin-severing gelsolin inhibits early HIV-1 infection during pore fusion formation or at a post-fusion step." (PMID 23575248, 2013). "In this matter, cell signals that upregulate or downregulate the expression of functional gelsolin, or that alter its cortical localization, may render putative target cells refractory to HIV-1 infection in vivo." (PMID 23575248, 2013). "Thus, we propose that gelsolin is a new factor that can limit HIV-1 infection acting at a pre-fusion step." (PMID 23575248, 2013). "Hence, endogenous gelsolin can act as a limiting factor for early HIV-1 infection at a pre-fusion step." (PMID 23575248, 2013). "Therefore, the level of expression of the gelsolin enzyme could restrict HIV-1 infection of CD4+ lymphocytes at a prefusion step." (PMID 37685911, 2023). "The studies of early HIV-1 infection by single-cycle viruses indicate that HIV-1 entry and infection is restricted when gelsolin is overexpressed." (PMID 23575248, 2013).
HIV-1 infection (continued). "It is conceivable that the expression of gelsolin may increase in permissive cells in response to specific signals, resulting in altered actin-cytoskeleton dynamics due to the severing of cortical actin filaments (i.e., bypassing the signals mediating by early HIV-1 infection)." (PMID 23575248, 2013). "Moreover, gelsolin silencing impairs early HIV-1 infection acting in a pre-fusion step, thereby preceding, and maybe abrogating cofilin-mediated post-fusion effects on HIV-1 infection." (PMID 23575248, 2013). "Thus, we propose that gelsolin is a new factor that can limit HIV-1 infection acting at a pre-fusion step, and accordingly, cell-signals that regulate gelsolin expression and/or its actin-severing activity may be crucial to combat HIV-1 infection." (PMID 23575248, 2013). "Overexpression of gelsolin-EGFP did not affect the cellular distribution or the cell-surface expression of CD4, CXCR4 or CCR5, the receptors required for HIV-1 infection (respectively)." (PMID 23575248, 2013). "Thus, the actin-severing gelsolin protein modulated HIV-1 entry and infection regardless of viral tropism, indicating that the inhibitory effect of gelsolin on early HIV-1 infection is not related to defective signalling or decreased cell-surface expression of viral co-receptors." (PMID 23575248, 2013).
Hypercholesterolemia (2 papers, 2015 to 2022). An increased concentration of cholesterol in the blood. "Interaction analysis showed that ACTB formed the hub of the revealed network, being involved in many interactions with other accessory proteins (e.g., with upregulated CAP1, WDR1, GSN, RHOA, and ARPC1A), suggesting myocardial cytoskeleton rearrangement in response to hypercholesterolemia." (PMID 35806390, 2022). "Six proteins including retinol-binding protein 4 (RBP4), transthyretin (TTR), gelsolin, haptoglobin, complement factor B (CFB) and CD5 antigen-like protein (CD5L) were identified to play imperative roles in lipid metabolism and inflammatory processes as a consequence of hypercholesterolemia." (PMID 27103892, 2015).
IgA Nephropathy (2 papers, 2017 to 2022). "Localization of gelsolin to the kidneys was also demonstrated in IgA nephropathy patients and these levels correlated with renal fibrosis while plasma gelsolin in these same patients was decreased." (PMID 35208209, 2022).
Insulin resistance (2 papers, 2023 to 2024). Increased resistance towards insulin, that is, diminished effectiveness of insulin in reducing blood glucose levels. "Furthermore, AFM, GSN, CFH, HGFAC, MMP2, and MMP9 have been previously associated with NAFLD or NAFLD-related factors such as liver damage, insulin resistance, metabolic syndromes, and extracellular homeostasis." (PMID 38034020, 2023). "Six proteins function in regulating glucose homeostasis, insulin resistance, and β-cell function, including SHBG, FETUB, PRG4, GSN, CFD, and TF, among which SHBG and FETUB are markers of insulin sensitivity and the expression of TF in adipose tissue is positively associated with insulin sensitivity." (PMID 38182717, 2024).
meningioma (2 papers, 2023). A generally slow growing tumor attached to the dura mater. "In addition to these markers, we identified Gelsolin (GSN) as a significantly downregulated protein in high grade meningioma." (PMID 37770851, 2023).
metabolic syndrome (2 papers, 2023). A cluster of metabolic risk factors for CARDIOVASCULAR DISEASES and TYPE 2 DIABETES MELLITUS. "The identified carbonylated proteins, including gelsolin, are potential targets that may act as key regulators in the progression of the metabolic syndrome." (PMID 37107219, 2023). "Our findings suggest that functional changes related to carbonylated modification of glycerol-3-phosphate dehydrogenase [NAD+] and gelsolin by oxidative stress may contribute to the development of the metabolic syndrome." (PMID 37107219, 2023). "Functional changes related to carbonylation of glycerol-3-phosphate dehydrogenase [NAD+] and gelsolin could also be involved in further worsening of the metabolic syndrome." (PMID 37107219, 2023). "The results showed that progression of obesity and development of the metabolic syndrome is associated with decreased antioxidant capacity of the adipose tissue, with a resultant increase in oxidative damage to proteins, including glycerol-3-phosphate dehydrogenase [NAD+] and gelsolin." (PMID 37107219, 2023).
metastatic disease (2 papers, 2012 to 2015). "The potential contributions of gelsolin towards the further spread of tumor cells from liver metastases warrant further investigations into the roles of cytoskeletal proteins in metastatic disease." (PMID 22927998, 2012).
myelodysplastic syndrome (2 papers, 2020 to 2023). A clonal hematopoietic disorder characterized by dysplasia and ineffective hematopoiesis in one or more of the hematopoietic cell lines. "However, the role of human plasma gelsolin in late stage erythroblasts prior to enucleation and putative clinical relevance in patients with myelodysplastic syndrome (MDS) and hemato-oncologic diseases have not been reported." (PMID 32992584, 2020).
Nephropathy (2 papers, 2018 to 2023). A nonspecific term referring to disease or damage of the kidneys. "Decreased gelsolin levels were correlated with progress of renal disease, 1-year mortality, and levels of circulating actin, detectable during analysis in those patients." (PMID 30149613, 2018). "Eight heterozygous variants were identified in nephropathy-associated genes (CLCN2, C5orf42, GSN, LMX1B, CEP164, PKD1, ITGB4, and KANK2), but each could be discounted having been inherited from an unaffected parent." (PMID 37148394, 2023).
nephrotic syndrome (2 papers, 2022 to 2026). A collection of symptoms that include severe edema, proteinuria, and hypoalbuminemia; it is indicative of renal dysfunction. "While renal involvement usually manifests as mild and intermittent proteinuria in heterozygotes for pathogenic variants in the GSN (Gelsolin) gene, homozygous patients for such variants present significant proteinuria and may develop nephrotic syndrome as early as in their early twenties." (PMID 36197414, 2022).